RYR2 (ryanodine receptor 2)
Diseases named in the same sentence as RYR2 in open-access papers (continued):
Sharing a sentence is not in itself a finding about the gene and the disease.
ventricular tachycardia (21 papers, 2010 to 2026). A disorder characterized by an electrocardiographic finding of three or more consecutive complexes of ventricular origin with a rate greater than a certain threshold (100 or 120 beats per minute are commonly used). "It has been proposed that CPVT1 or ventricular tachycardia (VT)-associated RyR2 mutations similarly increase the sensitivity of the channel to luminal Ca2+, which results in an increased open probability of the channel causing aberrant releases of calcium." (PMID 37894987, 2023). "Mutations in RyR1 and RyR2 lead to life-threatening malignant hyperthermia episodes and ventricular tachycardia, respectively." (PMID 36311249, 2022). "The disruption of RYR2 was associated with ventricular dysplasia and ventricular tachycardia in humans, whereas it is mainly associated with an increased heart rate and ventricular tachycardia in the mouse." (PMID 35924220, 2022). "Mutations in RYR2 are frequently reported in ventricular tachycardia and arrhythmogenic right ventricular dysplasia type 2." (PMID 31480292, 2019). "For example, mutations of RyR1 C-terminal region (3916–4973) are often observed in CCD, and mutations of RyR2 C-terminal region (3778–4959) cause inherited ventricular tachycardia." (PMID 24130701, 2013). "Moreover, the mutations of RYR2 or CASQ lead to Ca2+ leak in ventricular tachycardia and thus contribute to Ca2+ waves in arrhythmogenic as a result of the increasing Ca2+ spark frequency and rising flux." (PMID 35924220, 2022). "Moreover, the mutations of RYR2 or CASQ lead to Ca2+ leak in ventricular tachycardia, thus contributing to Ca2+ waves in arrhythmogenic as a result of the increasing Ca2+ spark frequency and rising flux." (PMID 35924220, 2022). "In a first pilot study we screened 35 unrelated patients from our Kazakhstani ventricular tachycardia study cohort suffering from ventricular tachycardia (most of them idiopathic) for genetic variants in the mutational hot-spot regions of the RYR2 gene and classified the observed variants." (PMID 24978818, 2014). "Defective closure of RyR2 channels results in intracellular calcium leakage, which leads to increased potential for delayed after-depolarizations and subsequent ventricular tachycardia." (PMID 41300725, 2025). "Our murine RyR2-R2474S platform thus recapitulated the exercise-induced ventricular tachycardia phenotypes previously reported in such patients." (PMID 39697246, 2024). "CaMKII inhibition by KN-93 was also shown to reduce the incidence of stress-induced ventricular tachycardia in a junction knock-out mouse model which presents with a phenotype similar to CPVT (RyR2 channels display CaMKII-dependent hyperphosphorylation)." (PMID 33013458, 2020). "Therefore, the dysfunction of the SR membrane calcium channel receptor RYR2 secondary to reduced RyR2-stable subunits may be associated with the development of AF or ventricular tachycardia through the common pathway via SR Ca2+ leakage and abnormal release-triggered activity." (PMID 30450052, 2018). "Sudden cardiac death or aborted cardiac arrest also appear in patients carrying certain RyR2 mutations but have not shown prior symptoms or history of recurrent ventricular tachycardia." (PMID 35457253, 2022). "Additionally, catecholamine-sensitive ventricular tachycardia is caused by RYR2 dysfunction, and low RYR2 expression likely causes a comparable range of negative effects." (PMID 37109540, 2023).
epilepsy (20 papers, 2017 to 2026). A brain disorder characterized by episodes of abnormally increased neuronal discharge resulting in transient episodes of sensory or motor neurological dysfunction, or psychic dysfunction. "Genes such as SCN5A, KCNQ1, KCNH2, RYR2 are associated with both channelopathies and epilepsy and almost 40% of people with LQT2 and 20% of those with LQT1 present an epileptic phenotype." (PMID 41062843, 2026). "Increased phosphorylation of RyR2 can lead to RyR2 Ca2+ leak, and leaky RyR2 has been linked to seizures, epilepsy, and sudden death." (PMID 37188671, 2023). "In this regard, it is of interest to know that the LOF RyR2 G4935R mutation identified in an 8 years old girl who suffered from SUD was initially given a clinical diagnosis of epilepsy." (PMID 33825858, 2021). "The frequency of the RYR2 variants in the cohort of epilepsy was significantly higher than that in control populations in gnomAD." (PMID 33897349, 2021). "Taken together the data from gene expression profile and RYR2 deficiency animal model, it is suggested that RYR2 was potentially a causative gene epilepsy." (PMID 33897349, 2021). "Previous studies in animals have indicated that the RYR2 deficiency is associated with epilepsy or alterations of electrical conduction in nerve cells." (PMID 33897349, 2021). "The occurrence and significance of cardiac phenotype in epilepsy patients with RYR2 mutations and their long-term outcome need further observation and follow-up." (PMID 33897349, 2021). "Special attention should be paid to the patients with RYR2 mutations due to the coexistence of epilepsy and heart disease, which potentially were potentially associated with SUDEP." (PMID 33897349, 2021). "The results of clinical validity summary matrix were 12 points that was categorized as “strong,” supporting the association between RYR2 variants and epilepsy." (PMID 33897349, 2021). "Strong evidence from ClinGen Clinical Validity Framework suggested an association between RYR2 variants and epilepsy." (PMID 33897349, 2021). "The evidence from ClinGen Clinical-Validity Framework also supports a strong association between RYR2 mutations and epilepsy." (PMID 33897349, 2021). "Evaluating the clinical validity of RYR2-epilepsy associations based on the framework developed by the clinical genome resource." (PMID 33897349, 2021). "As an 11 years old boy carrying the RyR2-R2401H mutation was long-term diagnosed with epilepsy instead of CPVT." (PMID 34725342, 2021). "As suggested by the literature, RYR2 mutations could lead to epilepsy and heart disease and are potentially associated with SUDEP." (PMID 41300725, 2025). "There are also data that show that a significant proportion of patients with this mutation of the RyR2 gene may have brain involvement with the presence, for example, of epilepsy and language delay." (PMID 36975861, 2023). "In conclusion, we identified a novel RYR2 mutation in a case of childhood-onset focal epilepsy, suggesting that RYR2 mutations may cause epilepsy in humans." (PMID 36340715, 2022). "These evidences suggest RYR2 mutations were potentially associated with epilepsy." (PMID 33897349, 2021). "We evaluated the RYR2 variants-epilepsy correlation using ClinGen Clinical-Validity Framework." (PMID 33897349, 2021). "Importantly, careful follow-up and specialized health consultation should be required for patients with RYR2 mutation, who may present epilepsy and heart disease." (PMID 36340715, 2022). "However, it is unknown whether RYR2 mutations were associated with more severe forms of epilepsy, and the whole spectrum of phenotype of RYR2 mutations warrants further studies." (PMID 33897349, 2021). "Thus, special attention should be paid to the patients with RYR2 mutations, who may present benign epilepsy such as BECTS but potentially require careful follow-up and specialized health consultation due to the coexistence of epilepsy and heart disease." (PMID 33897349, 2021).
epilepsy (continued). "Therefore, larger numbers of cases and further studies are needed to confirm whether different RYR2 mutations are related to more severe forms of epilepsy, and expand the whole spectrum of phenotype of RYR2 mutations, revealing the correlation between the variant and the patient's phenotype." (PMID 36340715, 2022). "A recent study identified an RYR2 mutation in a family with CPVT, in which an affected individual presented epilepsy." (PMID 33897349, 2021). "Patients with cardiac gene mutations have increased rates of neurological disorders: high rates of epilepsy in patients with LQT2 syndrome due to KCNH2 mutations and high rates of neurodevelopmental delay in patients with CPVT due to RYR2 mutations." (PMID 34930847, 2021). "Nevertheless, the role of leaky RyR2 in the pathogenesis of epilepsy has been described in the RyR2-R2474S mice model." (PMID 33271984, 2020). "A recent study linked a RyR2 missense variant with epilepsy in a 32-year old female without cardiac abnormalities while her brother – carrying the same mutation – had CPVT." (PMID 38444585, 2024). "Taken together the facts that RYR-2 is highly expressed in the brain and that RYR2 knockout animals presented increased cellular excitability, it is considered that RYR2 gene is potentially a candidate pathogenic gene of epilepsy." (PMID 33897349, 2021). "A study also evaluated the RyR2 involvement in epilepsy for CPVT patients." (PMID 34725342, 2021). "However, no study has yet confirmed whether changes in the expression level of RYR2 in the brain directly lead to epilepsy." (PMID 36340715, 2022). "However, the relationship between RYR2 and epilepsy is unclear." (PMID 33897349, 2021). "Patients with a prior epilepsy diagnosis constituted 5 of 19 for LQTS probands (3 KCNH2 and 1 KCNQ1), 2 of 15 for CPVT probands (1 RYR2), and 1 of 15 for BS probands (1 SCN5A)." (PMID 32298319, 2020). "KCNN4, and RYR2) in proband with CAE and the father also has seizure disorder." (PMID 28074849, 2017). "Thus, increased RyR2 NTD-CSol inter-subunit interaction may be a mechanism that underpins neurocardiac calcium channelopathies manifesting as CPVT and/or epilepsy." (PMID 39777228, 2024). "However, the relationship between RYR2 gene and epilepsy is not well determined." (PMID 36340715, 2022). "However, the relationship between RYR2 gene and epilepsy is not determined." (PMID 33897349, 2021).
breast cancer (19 papers, 2014 to 2025). A primary or metastatic malignant neoplasm involving the breast. "Previous research found that RYR2 mutation was significantly associated with better clinical prognosis and reduced the risk of development in breast cancer." (PMID 35874676, 2022). "RYR2 is frequently mutated in breast cancer, and its mutations can enhance the infiltration of cytotoxic T lymphocytes, activate memory CD4+ T cells and M1 macrophages to enhance antitumor immune responses." (PMID 36176287, 2022). "After screening, source genes closely associated with canine mammary tumours were found to include RYR2, PDE4D, ROCK2, CREB3L2 and UBA3, and associated circRNAs included chr27:26618544-26687235-, chr26:8194880-8201833+ and chr17:7960861-7967766-." (PMID 35622733, 2022). "Recent studies demonstrated that RYR2 was significantly mutated in multiple cancers, and RYR2 was reported to be a driver gene in cervical cancer, colon cancer, breast cancer, head and neck cancer, and lung adenocarcinoma." (PMID 34079583, 2021). "The opposite is true for other genes, like TTN, MUC4 and RYR2, which are amongst the most frequently mutated genes in breast cancer, but were clearly deprioritized by SomInaClust." (PMID 25903787, 2015). "Additionally, a correlation has been demonstrated between low RYR2 expression and unfavorable prognoses in patients diagnosed with thyroid and breast cancer patients; however, mutations at these loci remain underexplored in OV." (PMID 40990020, 2025). "Recurrent mutations of RYR2 have been reported in several human carcinomas, including squamous cell carcinoma of the oral cavity and lung, esophageal adenocarcinoma and breast cancer." (PMID 37079639, 2023). "We ascertained allele frequencies of the RYR2 variants in a collective of 288 unrelated individuals of Kazakh background (96 Breast cancer patients, 192 healthy control individuals) and only identified variant p.V1810L in an unrelated female breast cancer patient." (PMID 24978818, 2014). "This is reflective of breast cancer associations reported in the literature [KMT2C:, DMD:, TTN:, RYR2:]." (PMID 40685627, 2025). "Another candidate, RYR2, encodes for a ryanodine receptor, a component of a calcium channel, and it has been previously demonstrated that altered cellular calcium homeostasis contributes to the EMT in breast cancer." (PMID 34439480, 2021). "RYR2 has a linear, negative association with the hazard for breast cancer patients." (PMID 40685627, 2025). "Indeed, it was described that upon the EMT of MDA-MB-468 breast cancer cells, there was a drastic increase in RYR2, indicating that this receptor may play an important role in the process." (PMID 34439480, 2021).
Alzheimer disease (15 papers, 2014 to 2026). A progressive, neurodegenerative disease characterized by loss of function and death of nerve cells in several areas of the brain leading to loss of cognitive function such as memory and language. "However, RYR2 variants can be associated with abnormal Ca2+-handling in association with Alzheimer’s disease." (PMID 33562224, 2021). "Moreover direct injections into the hippocampi of amyloid beta peptide oligomers (AβOs), which are causative agents of Alzheimer’s disease, by engaging oxidation-mediated reversible pathways, increase single RyR2 channel activation by Ca2+ and cause considerable spatial memory deficits." (PMID 40076722, 2025). "Mutations in type 2 ryanodine receptors (RyR2) may lead to cardiac arrhythmias, such as catecholaminergic polymorphic ventricular tachycardia and arrhythmogenic cardiomyopathy, and to cognitive dysfunctions, such as Alzheimer’s disease." (PMID 39457698, 2024). "In murine models of Alzheimer’s disease, neuronal RyR2 channels were leaky, and treatment with the Rycal S107 reduced amyloid production and improved cognitive and behavioral function in mice." (PMID 36647824, 2023). "In human neurodegenerative disorders with cognitive dysfunction, particularly in Alzheimer’s disease, RyR2 has been shown to be downregulated." (PMID 32641776, 2020). "This was important because, apart from post-translation modifications of RyR2, downregulation of RyR2 expression levels was observed in both, humans samples and an animal model of Alzheimer’s disease." (PMID 32641776, 2020). "Indeed, we previously showed that oxidation, nitrosylation, and PKA phosphorylation of RyR2 results in leaky channels that contribute to the pathophysiology of posttraumatic stress disorder and Alzheimer’s disease (AD)." (PMID 32897880, 2020). "Our group also attested the existing connection between neuronal RyR2 dysfunctions and neurodegenerative disorders, notably the occurrence of the Alzheimer disease (AD)." (PMID 34725342, 2021). "This approach allowed us to identify compensatory mechanisms of neuronal and circuit excitability, which may likely contribute to the dysfunctions found in Alzheimer’s disease where both RyR2 downregulation and altered network excitability has been reliably observed." (PMID 32641776, 2020). "Since altered regulation of RyR2 expression has been observed in pathological conditions such as Alzheimer’s disease, the observation of compensatory mechanisms on the level of neuronal excitability, neuronal morphology and network function might provide important pathophysiological insights." (PMID 32641776, 2020). "Cognizant of the long history of a possible role for Ca2+ abnormalities in Alzheimer’s disease, we further looked into that disorder, as well as PTSD, and found roles for leaky RyR2 channels in both; more recently, we found possible involvement in the brain fog associated with long COVID." (PMID 36647824, 2023).
ventricular fibrillation (15 papers, 2010 to 2024). A disorder characterized by an electrocardiographic finding of a rapid grossly irregular ventricular rhythm with marked variability in QRS cycle length, morphology, and amplitude. "Two of the three patients with RYR2 variants had ventricular fibrillation and severe DCM which could be explained by post-arrest changes." (PMID 37795486, 2023). "In accordance with this prediction, the first mutation in the RyR2 associated with ventricular fibrillation (A4860G), which dramatically reduces RyR2 opening, was recently described and shown to be associated with a strong reduction in luminal calcium activation of the RyR2." (PMID 23390511, 2013). "One patient with ventricular fibrillation, dilated LV, and features compatible with left ventricular non-compaction cardiomyopathy (LVNC) had the common pathogenic RYR2 exon 3 deletion, c.(168 + 1_169-1)_(273 + 1_274-1)del, as a de novo variant." (PMID 37795486, 2023). "The LVNC caused by RYR2, KCNQ1, and KCNH2 mutations occurred with catecholamine-sensitive VT, long QT syndrome (LQTs), torsade de pointes, and ventricular fibrillation." (PMID 34819141, 2021). "Ventricular fibrillation (VF) results in increased diastolic calcium leaks from the sarcoplasmatic reticulum via ryanodine receptor subtype 2 (RyR2) within cardiac myocytes." (PMID 28098197, 2017). "Genetic testing is recommended for CPVT-susceptibility genes—RyR2, CASQ2, CALM1-3, TRDN and TECRL—in all probands with a definitive clinical diagnosis of CPVT and may be considered in individuals with idiopathic ventricular fibrillation (VF) upon identification of an adrenergic trigger." (PMID 38542006, 2024).
arrhythmogenic right ventricular cardiomyopathy (14 papers, 2009 to 2026). "RyR2 mutations can also cause arrhythmogenic right ventricular cardiomyopathy (ARVC), which is characterized by fatty infiltration and fibrosis of the myocardium." (PMID 31143551, 2019).
channelopathy (13 papers, 2016 to 2026). Channelopathies are a group of diseases caused by the dysfunction of ion channel subunits or their interacting proteins. "It is classified as channelopathy, indicating a gene mutation that translates to specific ion channels in the cardiac myocytes, namely ryanodine receptor-2 (RyR2) and calsequestrin-2 (CASQ2) channels." (PMID 38034271, 2023). "Mutations involved 3 channelopathy-associated genes (RYR2, CACNA1C, and ANK2), 3 HCM- or DCM-associated genes (MYH7, LDB3, and PRKAG2), 5 ACM-related genes (PKP2, JUP, DSG2, DSP, and TMEM43), and 2 cardiac transcription factor genes (TBX5 and GATA4)." (PMID 34441312, 2021). "We find that FKBP12 and FKBP12.6 (hereafter FKBP12/12.6) removal from sheep RyR2 is correlated with increased sub-conductance activity in one RyR2 channelopathy linked to a mutation in the RyR2-associated regulatory protein CLIC-2." (PMID 31028179, 2019). "The variants included three channelopathy-associated genes (RYR2, CACNA1C, and ANK2), three HCM- or DCM-associated genes (MYH7, LDB3, and PRKAG2), five ACM-related genes (PKP2, JUP, DSG2, DSP, and TMEM43), and two cardiac transcription factor genes (TBX5 and GATA4)." (PMID 39272661, 2024). "CNVs involving single or multiple exons of the major channelopathy genes, KCNQ1, KCNH2, SCN5A, and RYR2, uncommonly serve as the pathogenic basis of dominantly inherited arrhythmia syndromes such as long QT syndrome, Brugada syndrome, and CPVT." (PMID 32663189, 2020). "The channelopathies are associated with the following genes: SCN5A, KCNQ1, KCNH2, KCNE1, RYR2." (PMID 38793126, 2024). "It is possible that attenuated β-blocker efficacy is RyR2 mutation-specific, as KCNQ1 mutation-specific responses to β-blocker therapy have been observed in type I long QT syndrome, another inherited arrhythmogenic channelopathy." (PMID 27491078, 2016). "When the autopsy does not show any structuralcardiac anomaly, channelopathies he following panel of genes: SCN5A, KCNQ1, KCNH2, KCNE1, and RYR2 should be used." (PMID 38793126, 2024).